HOXB13 (homeobox B13)
Diseases named in the same sentence as HOXB13 in open-access papers (continued):
Sharing a sentence is not in itself a finding about the gene and the disease.
esophageal squamous cell carcinoma (7 papers, 2017 to 2025). Esophageal squamous cell carcinoma (ESCC) is a type of esophageal carcinoma (EC) that can affect any part of the esophagus, but is usually located in the upper or middle third. "In esophageal squamous cell carcinoma, homeobox B13 (HOXB13) is significant in tumorigenesis, overexpression of CDR1as abrogates miR-7 from suppressing HOXB13, promoting malignant progression in patients." (PMID 40251826, 2025). "For example, HOXB13 was reported to be able to mediate NF-κB/p65 pathway and regulate the proliferation and metastasis of esophageal squamous cell carcinoma." (PMID 33179733, 2020). "The migration and invasion of esophageal squamous cell carcinoma (ESCC) is positively correlated with CDR1as, CDR1as acts as an miR-7 sponge to promote tumor progression by increasing the function of the stem cell marker Klf-4 and homeobox gene B13 (HOXB13)-mediated nuclear factor (NF-κB)." (PMID 32765960, 2020).
renal cell carcinoma (7 papers, 2012 to 2023). "In renal cell carcinoma lines and primary tumors, HOXB13 methylation status is correlated with a loss of HOXB13 expression, which is also associated with tumor grade and microvessel invasion." (PMID 38068717, 2023). "In addition, HOXB13 methylation (loss of expression) in renal cell carcinoma was positively correlated with tumor grade and invasion." (PMID 37627895, 2023).
hepatocellular carcinoma (6 papers, 2015 to 2026). A malignant tumor that arises from hepatocytes. "In hepatocellular carcinoma (HCC), HOXB13 expression is significantly elevated in tumor tissues compared to adjacent non-tumorous tissues, and its high expression correlates with advanced clinical stage and poor prognosis." (PMID 41023726, 2025).
lymph node metastasis (5 papers, 2017 to 2025). "Additionally, HOXB13 expression was associated with lymph node metastasis, histological stage, and tumor grade." (PMID 38792899, 2024). "They found HOXB13 positivity in 33% of bone metastases and 93% of lymph node metastases." (PMID 28555048, 2017). "While our current cohort included only lymph node metastases, previous studies of metastatic CRPC (including liver and bone metastases) similarly demonstrated consistent HOXB13 downregulation, supporting its broader role in advanced metastasis beyond LNs." (PMID 41277556, 2025).
hereditary prostate cancer (4 papers, 2016 to 2025). "The HOXB13 gene has been associated with hereditary prostate cancer (PCa), with rare germline variants linked to early-onset and aggressive forms of the disease." (PMID 41188766, 2025).
leukemia (4 papers, 2019 to 2022). A malignant (clonal) hematologic disorder, involving hematopoietic stem cells and characterized by the presence of primitive or atypical myeloid or lymphoid cells in the bone marrow and the blood. "The recurrent mutation of G84E in the MEIS-interacting domain of HOXB13 has been reported to be associated with leukemia and other cancers in a clinical correlation research." (PMID 33037410, 2020). "Increased Suv39h1 expression led to the inactivation of Hoxb13 and Six1, as well as reversion of Hoxa9/Meis1 downstream target genes, which in turn decelerated leukemia progression." (PMID 33037410, 2020). "Herein, we demonstrate that Suv39h1 is significantly down-regulated in AMLs and could function as a tumor suppressor in MLL-rearrangement induced leukemia by regulating Hoxb13 and Six1, as well as Hoxa/Meis1 downstream signature genes." (PMID 33037410, 2020). "By restoration of the Hoxb13 expression in SUV-OE AML cells, we found an accelerated leukemia progression in SUV-OE AML mice, indicating that Hoxb13 restoration abolished the effect of SUV-OE on prolonged survival of MLL-r AML mice." (PMID 33037410, 2020). "We reasoned that the lower expression levels of HOXA9 and HOXA10 probably were a reflection of slower progressing of leukemia rather than a HoxB13 shRNA non-specific knockdown effect on the HoxA family members." (PMID 33037410, 2020). "Furthermore, restoration of Hoxb13 in SUV-OE AML cells accelerated the leukemia progression and increased the number of LSCs, suggesting Hoxb13 is a downstream effector of Suv39h1 in MA9 leukemia cells." (PMID 33037410, 2020).
colorectal tumor (3 papers, 2005 to 2019). "Loss of HOXB13 in colorectal tumor cells has been associated with the increase in proliferation." (PMID 31324852, 2019). "Our results suggest that loss of HOXB13 may be an important event for colorectal cell transformation, considering that over 90% of colorectal tumours retain mutations in the APC/β-catenin pathway." (PMID 15928669, 2005). "In other words, loss of HOXB13 may stimulate the expression of c-myc to help the colorectal tumour development." (PMID 15928669, 2005). "To study the role of HOXB13 in colorectal tumorigenesis, we evaluated the expression of HOXB13 in 53 colorectal tumours originated from the distal left colon to rectum with their matching normal tissues using quantitative RT–PCR analysis." (PMID 15928669, 2005). "In this study, we investigated the expression of HOXB13 in colorectal tumours and the involvement of HOXB13 in the β-catenin/TCF signalling pathway." (PMID 15928669, 2005). "In this study, we demonstrated that expression of HOXB13 is frequently diminished in colorectal tumours to confer a positive growth signal, which may be accomplished thorough the regulation of β-catenin/TCF4 signals." (PMID 15928669, 2005). "Since the DNA methyltransferase DNMT3b plays an important role in methylation of cancer-related genes, and HOXB13 was reported to be a target gene of DNMT3b in primary colorectal tumors, we speculated that DNMT3b may also be involved in HOXB13 transcriptional repression in DU145 cells." (PMID 22808286, 2012). "HOXB13 seems to function as a growth suppressor by negatively regulating signals from the CRT pathway, which is usually aberrantly activated in colorectal tumours." (PMID 15928669, 2005). "Next, we investigated whether HOXB13 is involved in the regulation of β-catenin-TCF-regulated transcription (CRT), which is constitutively activated in most colorectal tumours." (PMID 15928669, 2005).
ependymoma (3 papers, 2010 to 2025). A WHO grade II, slow growing tumor of children and young adults, usually located intraventricularly. "One sample (1%) had no match for any DNA methylation type in classifier V12.5 but was HOXB13 positive, showed distinct features of a myxopapillary ependymoma with an SP-MPE-A subtype in the t-SNE visualization, and was therefore assigned as SP-MPE." (PMID 39713042, 2024). "Immunohistochemical studies reported on strong nuclear HOXB13 expression in MPE, while other types of ependymoma and spinal astrocytomas showed only weak or absent HOXB13 positivity." (PMID 40137996, 2025).
lung adenocarcinoma (3 papers, 2020 to 2021). A carcinoma that arises from the lung and is characterized by the presence of malignant glandular epithelial cells. "Patients enrolled in studies have shown that high HOXB13 expression promotes the progression of lung adenocarcinoma and predicts poor prognosis." (PMID 34722321, 2021). "In particular, we take the example of the role of HOXB13 in mediating chemotherapy resistance in lung adenocarcinoma." (PMID 34722321, 2021). "Levels of HOXB13 and its target genes may help predict sensitivity of platinum-based chemotherapy in lung adenocarcinoma patients." (PMID 34722321, 2021).
lung carcinoma (3 papers, 2015 to 2025). "For example, HOXB13 have tumor suppressive effects in prostate and lung cancers, and oncogenic effects in ovarian and breast cancers." (PMID 26219418, 2015).
metastatic disease (3 papers, 2022 to 2025). "Future analyses of HOXB13 in metastatic tumors, such as liver, lung, and bone, of HN PCa relative to primary sites will further clarify this point." (PMID 41277556, 2025).
metastatic prostate carcinoma (3 papers, 2019 to 2025). A carcinoma that arises from the prostate gland and has spread to other anatomic sites. "Overall, our study reveals HOXB13 as a master transcriptional regulator of PC metastasis and has identified actionable targets for the treatment of HOXB13 overexpressing primary and metastatic prostate cancers." (PMID 31273254, 2019).
renal carcinoma (3 papers, 2019 to 2022). A carcinoma arising from the epithelium of the renal parenchyma or the renal pelvis. "HOX genes have been demonstrated to impact tumorigenesis directly via diverse mechanisms in cancer, and HOXB13 has been shown to play a critical regulatory role in renal cancer." (PMID 30975094, 2019). "We consider that although HOXB13 participates in the Wnt pathway, it may be different from the receptor of renal carcinoma." (PMID 34306077, 2021).
cervical cancer (2 papers, 2017). A primary or metastatic malignant neoplasm involving the cervix. "In our study, the decreased HOXA10 expression and increased HOXB13 expression were associated with reduced E-Cadherin and enhanced Vimentin expression, proposing the need for further studies to establish HOXA10 and HOXB13 as biomarkers of metastasis in cervical cancer." (PMID 28402266, 2017). "Thus the correlation plots of HOXA10 and HOXB13 with the EMT markers, suggest a role of HOXA10 and HOXB13 in driving metastasis in cervical cancer." (PMID 28402266, 2017).
esophageal cancer (2 papers, 2021 to 2023). A primary or metastatic malignant neoplasm involving the esophagus. "LncRNA ENST00000500112 (LncRNA CCAT1), which was upregulated in CRC and esophageal cancer, by adjusting the expression of HOXB13 and SPRY4 affect cell proliferation and migration in esophageal squamous carcinoma." (PMID 33493136, 2021). "The same function was observed in esophageal carcinoma by regulating SPRY4 and HOXB13 expression." (PMID 36624401, 2023).
glioblastoma (2 papers, 2019 to 2021). The most malignant astrocytic tumor (WHO grade IV). "High HOXB13 expression is associated with poor survival rates for patients with glioblastoma, which may be due to the upregulation of long noncoding RNA HOXC-AS3 transcription." (PMID 33315534, 2021).
kidney cancer (2 papers, 2022 to 2024). Primary or metastatic malignant neoplasm involving the kidney. "It is noteworthy that the HOXB13 gene is located on chromosome 17q, the loss of heterozygosity of which has been noted in cancer of the kidney, breast, ovary, colon and some haematological malignancies." (PMID 34983599, 2022). "Among 813 kidney cancer cases HOXB13 mutations was reported in three patients (0,4%) (odds ratio [OR], (OR = 2,8; 95% CI 0.69–11.11; p = 0.3)." (PMID 34983599, 2022). "Our goal was to determine the prevalence of HOXB13 p.G84E mutation in bladder and kidney cancer patients from Poland." (PMID 34983599, 2022). "Based on a review of the evidence in the literature, there are several studies that investigate the effect of the p.G84E mutation in the HOXB13 gene in unselected bladder and kidney cancer cases, but they are based on small study cohorts." (PMID 34983599, 2022). "Previous studies demonstrated HOXB13 as a tumor suppressor in colon and kidney cancer." (PMID 38792899, 2024). "Previous studies have suggested that HOXB13 functions as a tumor suppressor in colon and kidney cancers and that inactivation of HOXB13 may play an important role in tumor formation and metastasis." (PMID 38792899, 2024). "In conclusion, this study reveals that the p.G84E mutation in the HOXB13 gene does not seem to play a role in development of bladder or kidney cancer." (PMID 34983599, 2022). "In this study, we found no impact of the p.G84E mutation in the HOXB13 gene on bladder or kidney cancer." (PMID 34983599, 2022). "Mutation p.G84E in HOXB13 seem not to play a role in bladder and kidney cancer development in Polish patients." (PMID 34983599, 2022).
myocardial infarction (2 papers, 2020 to 2021). Gross necrosis of the myocardium, as a result of interruption of the blood supply to the area, as in coronary thrombosis. "Double knockout of Meis1 and Hoxb13 (Homeobox B13), a cofactor of Meis1, reactivates cell cycle activity in adult cardiomyocytes, induces sarcomere disassembly and improves cardiac function following myocardial infarction." (PMID 34692797, 2021).
pancreatic cancer (2 papers, 2017 to 2019). "In the HoxB gene cluster, several members including HoxB2, HoxB5, HoxB6, and HoxB13 are over-expressed in pancreatic cancer." (PMID 31137902, 2019). "Interestingly, the expression of HoxA3 and HoxB8 was continuously upregulated in pancreatic cancer cells with increased metastatic ability, while the expression of HoxA10, HoxA11, and HoxB13 was consistently reduced in these cells." (PMID 31137902, 2019). "Moreover, high HoxB13 correlates with tumor angiogenesis and aggressive clinicopathological characteristics, and could serve as a promising marker for unfavorable prognosis in pancreatic cancer." (PMID 31137902, 2019).
small cell carcinoma (2 papers, 2019 to 2021). A neuroendocrine carcinoma composed of small malignant cells which are often said to resemble "oat cells" under the microscope. "Of the 9 NEPCa, there was only 1 small cell carcinoma stained weakly and focally (H-score of 2) with HOXB13 immunomarker." (PMID 33531604, 2021). "In contrast to the positive stain in AdPCa, no HOXB13 immunohistochemical reactivity was observed in 8 of 9 NEPCa including 8 small cell carcinoma and 1 neuroendocrine carcinoma, not otherwise specified." (PMID 33531604, 2021).
alopecia (1 paper, 2016). Hair loss usually from the scalp. "Loss of Hoxc13 expression in mice causes a fragile hair with an alopecia phenotype, and loss another HOX gene member, Hoxb13, promotes differentiation and enhances wound healing in adult skin." (PMID 27253709, 2016).
astrocytoma (1 paper, 2025).
atherosclerosis (1 paper, 2024). A disease characterized by the build-up of fatty material and calcium deposition in the arterial wall resulting in partial or complete occlusion of the arterial lumen. "Homeobox B13 (HOXB13) is a master regulator in cell differentiation, proliferation, and migration, particularly in vasculogenesis and vascular remodeling, which are common events during neointimal lesion formation in atherosclerosis and post angioplasty restenosis." (PMID 39595622, 2024).
childhood cancer (1 paper, 2021). "Taken together, the seven prioritized VUSs in CHEK2 and HOXB13 genes might confer an increased risk for childhood cancer." (PMID 33840814, 2021). "Next, by combination of the comprehensive clinical data of each patient with published data on VUSs, we identified six prioritized VUSs in CHEK2 and HOXB13 genes in seven patients for which we found strong evidence to confer an increased susceptibility to childhood cancer." (PMID 33840814, 2021).
chordoma (1 paper, 2021). Chordomas are rare malignant tumors arising from embryonic remnants of the notochord in axial skeleton. "The genes HOXB7, HOXB13, and HOXA-AS3 were detected among the upregulated genes in recurrent chordomas." (PMID 34330313, 2021).
diabetes (1 paper, 2015). "4EBP1 was also positively associated with genes coupled to diabetes pathways, genes regulated by the transcription factors E2F, USF and SP1, the oncogenes HRAS and HOXB13 and several genes involved in negative regulation of translational initiation (EIF4EBP2, EIF2B3, EIF2C2)." (PMID 26698305, 2015).
endometrioid carcinoma of ovary (1 paper, 2015). "Comparably high expression of HOXB13 was observed in HEY, SKOV3 and NOE (a new cell line of endometrioid carcinoma of ovary) cells; thus, we used these cells for further experiments." (PMID 25944620, 2015).
ependymal tumor (1 paper, 2025). A group of neoplasms which arise from the ependymal lining of the cerebral ventricles and from the remnants of the central canal of the spinal cord. "We assessed the diagnostic utility of HOXB13 immunohistochemistry in an institutional cohort of various types of spinal ependymal tumors (n = 111) and various other spinal tumor types (n = 32)." (PMID 40137996, 2025). "DNA copy number profiles of selected ependymal tumors and the cumulative copy number profiles of HOXB13-positive MPE vs. HOXB13-negative SP-EP are shown in Suppl." (PMID 40137996, 2025). "In addition to spinal ependymal tumors, we also evaluated immunohistochemical expression of HOXB13 in selected cases representing other types of primary spinal cord tumors." (PMID 40137996, 2025). "Taken together, immunohistochemistry for HOXB13 protein expression and targeted DNA methylation analysis of HOXB13 represent useful surrogate approaches that may substitute for DNA methylome profiling in routine diagnostics and facilitate precise classification of spinal ependymal tumors." (PMID 40137996, 2025).
head and neck cancer (1 paper, 2025). A primary or metastatic malignant neoplasm affecting the head and neck. "Given that NPC is classified under head and neck cancers, the expression level of HOXB13 in head and neck cancer was initially examined using the TCGA database, which revealed significantly higher HOXB13 expression in tumor tissues compared to normal tissues." (PMID 41023726, 2025).
heart failure (1 paper, 2013). Inability of the heart to pump blood at an adequate rate to meet tissue metabolic requirements. "We detected methylation differences in pathways related to heart disease, but also in genes with yet unknown function in DCM or heart failure, namely Lymphocyte antigen 75 (LY75), Tyrosine kinase-type cell surface receptor HER3 (ERBB3), Homeobox B13 (HOXB13) and Adenosine receptor A2A (ADORA2A)." (PMID 23341106, 2013).
hereditary cancer (1 paper, 2025). Malignant neoplasms occurring in families at a rate greater than that expected by chance and caused by germline mutations in a specific gene. "LP/P findings in pleiotropic genes linked to human development and hereditary cancer (TSC1, PHOX2B, WT1, SPRED1, NF1, LZTR1, HOXB13) were identified in several patients with syndromic phenotypes." (PMID 40060932, 2025).
hyperplasia (1 paper, 2025). An abnormal increase in the number of cells in an organ or a tissue with consequent enlargement. "A cohort of 13 TSPs, 6 EPTs, 17 ABCs, and 8 adenoid basal hyperplasia (ABH) was analyzed for expression of prostatic markers HoxB13, NKX3.1, p16, and androgen receptor (AR)." (PMID 41335140, 2025).
Hypertension (1 paper, 2022). The presence of chronic increased pressure in the systemic arterial system. "For HOXB13, it was reported that the knockdown of HOXB13 can reduce the cytotoxicity caused by various oxidative stress inducers, and an increasing number of studies suggest that oxidative stress has a key role in the pathogenesis of hypertension." (PMID 35213968, 2022).
liver fibrosis (1 paper, 2024). "A recent study identified strong localization of HOXB13 in patients with liver fibrosis, suggesting an important role for HOXB13 in the pathogenesis of liver fibrosis." (PMID 38792899, 2024). "As liver fibrosis is a major risk factor for HCC, it is important to understand the role and molecular functions of HOXB13 in HCC." (PMID 38792899, 2024).
metastatic cancer (1 paper, 2025). A carcinoma which has spread from the original site of growth to another anatomic site. "In summary, we have overcome the challenge of directly targeting the undruggable TF HoxB13 in metastatic cancer by developing the SCORT‐Cas13d‐gHoxB13 system." (PMID 40349174, 2025).
nasopharyngeal carcinoma (1 paper, 2025). A carcinoma arising from the nasopharyngeal epithelium. "HOXB13 has been shown to act as a tumor promoter in various malignancies; however, its role in nasopharyngeal carcinoma (NPC) remains unexplored." (PMID 41023726, 2025).